OR51B4 (olfactory receptor family 51 subfamily B member 4)
Description:
Odorant receptor.
Synonyms: HOR5'Beta1
Tractability: Antibody: UniProt places it where antibodies can reach, with medium confidence; UniProt predicts a signal peptide or a membrane-spanning region; its Gene Ontology location is reachable by antibodies, with medium confidence.
Gene: Protein-coding gene on chromosome 11 (5,301,014 to 5,301,946, reverse strand). Ensembl gene ENSG00000183251.
Subcellular location: Cell membrane
Pathways (Reactome):
Sensory Perception: Expression and translocation of olfactory receptors
Gene Ontology:
Molecular function: olfactory receptor activity; G protein-coupled receptor activity; signaling receptor activity
Biological process: sensory perception of smell; cellular response to lipid; detection of chemical stimulus involved in sensory perception of smell; G protein-coupled receptor signaling pathway; system process
Cellular component: membrane; plasma membrane
Genetic constraint (gnomAD): Loss-of-function variants: 0 observed, 0.65 expected, observed/expected ratio (o/e) 0, 90% interval 0 to 1.81. That is too few expected variants to judge how well the gene tolerates losing a copy. Missense variants: 400 observed, 398.41 expected, observed/expected ratio (o/e) 1, 90% interval 0.92 to 1.09. Synonymous variants: 147 observed, 147.68 expected, observed/expected ratio (o/e) 1, 90% interval 0.87 to 1.14.
Homologues: Orthologues: rabbit OR51B4 (81% identical), dog OR51B4 (79% identical), rat Or51b4b (76% identical), guinea pig OR51B4 (76% identical), rat Or51b4 (76% identical), mouse Or51b4 (75% identical). Paralogues in human: OR51B6 (67% identical), OR51B2 (65% identical), OR51B5 (64% identical), OR51G1 (48% identical), OR51G2 (48% identical), OR51V1 (47% identical), OR51L1 (47% identical), OR51F2 (44% identical), OR51I2 (44% identical), OR51A4 (43% identical), OR51M1 (43% identical), OR51A7 (43% identical), and 39 more.
Diseases named in the same sentence as OR51B4 in open-access papers:
OR51B4 is named in the same sentence as 10 diseases in open-access papers, as found by Europe PMC text mining. Sharing a sentence is not in itself a finding about the gene and the disease. The quoted sentences say what the papers report.
colon carcinoma (5 papers, 2015 to 2021). "Another olfactory receptor (OR), OR51B4, has been observed to be highly expressed in the colon cancer cell line HCT116." (PMID 34573430, 2021). "For instance, olfactory receptor OR51B4 is highly expressed in colon cancer HCT116 cells and the activation of the receptor by its ligand (Troenan) inhibited cell proliferation and apoptosis by phosphorylation of p38, mTOR, and Akt kinases." (PMID 31068808, 2019). "We also analyzed the transcriptomes of patients with colon carcinomas and liver metastases, which revealed the expression of OR51B4 in 3 out of 4 data sets." (PMID 28273117, 2017). "We identified OR51B4, which is highly expressed in the colon cancer cell line HCT116 and in native human colon cancer tissues." (PMID 28273117, 2017). "OR51B4 was detected in tissue samples of rectal and colon carcinoma." (PMID 28273117, 2017). "In this study, for the first time, we demonstrate the ectopic expression of the olfactory receptor OR51B4 in the colon cancer cell line HCT116 and reveal the influence of its activation by the cognate ligand Troenan on cell proliferation, migration, actin filament formation and apoptosis." (PMID 28273117, 2017). "Another study reported a high expression level of OR51B4 in the colon cancer cell line, HCT116, and in native human colon cancer tissues." (PMID 33566867, 2021). "Because the expression of OR51B4 is not restricted to HCT116, but rather is also present in two other colon cancer cell lines and is even expressed in native colon carcinoma tissues, the potential importance of OR51B4 for clinical research and treatment of colon cancer is underlined." (PMID 28273117, 2017).
colorectal cancer (5 papers, 2017 to 2021). A primary or metastatic malignant neoplasm that affects the colon or rectum. "Another member, OR51B4, is also over-expressed in colorectal cancer and induces apoptosis and limits cell migration and proliferation through activation by its ligand, Troenan." (PMID 33566867, 2021). "Elsewhere in the gastrointestinal tract, researchers have investigated the role of OR51B4 in colorectal cancer." (PMID 30542293, 2018). "As HCT116 serves as a model system for colorectal cancer, we investigated the expression of OR51B4 in several human cancer tissues." (PMID 28273117, 2017). "Although, among the ORs enriched in the pathway analysis, OR51B4 was not discovered in our cohorts, our findings suggest that ORs could be potential genes for further exploration in colorectal cancer research." (PMID 34573430, 2021).
cervical cancer (1 paper, 2017). A primary or metastatic malignant neoplasm involving the cervix. "OR51B4 is also expressed in some lung-, breast-, bladder- and cervical cancer tissues, leading to the assumption that this receptor might play a role in several different cancers." (PMID 28273117, 2017).
glioblastoma (1 paper, 2017). The most malignant astrocytic tumor (WHO grade IV). "Interestingly, OR51B4 is also expressed in several human neuroblastoma tissues and glioblastoma cell lines, e.g., SHEP, SK-N-SH and U87 (blue)." (PMID 28273117, 2017).
thalassemia (1 paper, 2014). An inherited blood disorder characterized by a decreased synthesis of one of the polypeptide chains that form hemoglobin. "Two SNPs in the upstream region of OR51B4 gene were found among genetic modifiers of Hb E/b0 thalassemia identified by a two-stage genome-wide association study." (PMID 24715883, 2014).
cancer (4 papers, 2017 to 2021). A tumor composed of atypical neoplastic, often pleomorphic cells that invade other tissues. "It has been observed that PSGR facilitates cancer cell proliferation, invasion, and migration, while OR2AT4 and OR51B4 hamper cancer cell behaviors." (PMID 31781505, 2019). "To determine the expression profile of OR51B4, we analyzed more cancer tissues and cell lines and produced a ranking of the expression values of OR51B4 in the different tissues and cell lines." (PMID 28273117, 2017). "These include OR51B4 and OR5K1 genes that are over‐expressed in HCT116 cells when compared to 947 cancer cell lines." (PMID 32141232, 2020).
tumour (1 paper, 2020). "OR51B4 and OR5K1 are mostly expressed in patients with tumour grade 3 or higher." (PMID 32141232, 2020).
OR51B4 also shares sentences with these, for which no sentence is quoted: breast carcinoma (1 paper); neuroblastoma (1); thyroid cancer (1).